CCL4 (C-C motif chemokine ligand 4)
Diseases named in the same sentence as CCL4 in open-access papers (continued):
Sharing a sentence is not in itself a finding about the gene and the disease.
ischemic stroke (2 papers, 2018 to 2023). A stroke disorder caused by obstruction of blood flow to the brain, due to thrombotic (local blood clot formation) or embolic (due to a blood clot or other material traveling from another site) event. "In summary, ischemic stroke results in upregulated expression of adhesion molecules (P‐selectin, E‐selectin, and ICAM‐1) and chemokines (CCL‐2, CCL‐3, CCL‐4, CCL‐5, and CXCL‐1)." (PMID 37122157, 2023). "Our results have revealed that ischemic stroke results in upregulated expression of adhesion molecules (P‐selectin, E‐selectin, and ICAM‐1) and chemokines (CCL‐2, CCL‐3, CCL‐4, CCL‐5, and CXCL‐1)." (PMID 37122157, 2023). "Ischemic stroke induces the release of different chemokines such as CCL-2, CCL-3, CCL-4, CCL7, CCL-11, CXCL-1, CXCL10, from the ischemic tissue." (PMID 30584250, 2018).
latent infection (2 papers, 2019 to 2022). "However, compared to MDV/RB1B infection, MDV/CVI988 infection resulted in a more effective transcriptional activation of CCL4 in the latent infection phase (7–14 dpi), which may be a characteristic distinguishing the vaccine MDV strain from the vvMDV strain." (PMID 36680047, 2022). "However, compared to MDV/RB1Binfection, MDV/CVI988 infection resulted in a more effective transcriptional activation of CCL4 in the latent infection phase (7–14 dpi), which may be a characteristic distinguishing MDV vaccine strain from the very virulent strain." (PMID 36680047, 2022). "In normal to latent infections, we identified eight genes, of which three genes (FZD2, NDUFS8, NLRC4) were up-regulated, and another five genes (CCL4, IL1B, IL1A, TNF, AREG) were down-regulated." (PMID 31749827, 2019).
leishmaniasis (2 papers, 2012 to 2024). Infectious disease that is transmitted through the bite of hematophagous female phlebotomine sand flies. "We took advantage of the published human dataset and a murine model of increased pathology induced by the colonization of S. epidermidis to evaluate whether there is an association between the Staphylococcal species colonization and the expression of CCL3 and CCL4 in the leishmaniasis lesions." (PMID 38709823, 2024). "It has been proposed that in leishmaniasis, chemokines CCL2, CCL4, and CCL5 generally play a role not only as chemotactic factors but also as co-activators of macrophages and consequently have a part in the elimination of parasites." (PMID 22506080, 2012).
lung disease (2 papers, 2009 to 2021). "Previous studies have found that the chemokine CCL4 exerts a vital part in the pathogenic mechanism of pulmonary diseases like bacterial pneumonia and respiratory defense." (PMID 34054345, 2021). "Among them, monocyte chemoattractant protein-1 (MCP-1 or CCL2) and macrophage inflammatory protein-1β (MIP1β or CCL4) may play a role in SSc, as the overexpression of these chemokines has been detected in SSc-related lung disease." (PMID 19615053, 2009). "Furthermore, studies have shown that CCL4 (MIP-β) chemokines exert vital parts within cytokine networks modulating immune and inflammatory responses of the respiratory tracts, which possibly facilitate the pathogenic mechanism of pulmonary diseases." (PMID 34054345, 2021).
lysosomal storage disease (2 papers, 2020 to 2023). A metabolic disorder caused by mutations in proteins critical for lysosomal function, including lysosomal enzymes, lysosomal integral membrane proteins, and proteins involved in the post-translational modification and trafficking of lysosomal proteins. "Increased expression of Ccl3 and Ccl4 in the brain and cerebellum were also observed in different lysosomal storage diseases such as MPSIIIA and MPSIIIB, and Gaucher disease." (PMID 32951593, 2020).
metastatic disease (2 papers, 2015 to 2022). "Some cytokines and chemokines, such as C-X-C motif chemokine ligand 10 (CXCL10), C-C motif chemokine ligand 4 (CCL4), CCL17, and IL-8, are also highly expressed in the CSF of metastatic tumors." (PMID 36531024, 2022).
metastatic melanoma (2 papers, 2015 to 2021). A melanoma that has spread from its primary site to another anatomic site. "A study looking at metastatic melanoma biopsies showed that up-regulation of several chemokines, including CCL2, CCL3, CCL4, CCL5, CXCL9, and CXCL10 could be correlated with the presence of T cells in the tumor." (PMID 34207884, 2021).
nasopharyngeal carcinoma (2 papers, 2020 to 2024). A carcinoma arising from the nasopharyngeal epithelium. "Sengupta dataset (41 patient samples) evaluated that expression of IFIT1 (p = 5.38 × 10−5), CCR4 (p = 0.046), and CCL4 (p = 2.79 × 10−8) genes were increased in nasopharyngeal carcinoma compared with normal nasopharynx." (PMID 32961854, 2020). "Nasopharyngeal carcinoma (NPC) is a neoplasm related to inflammation; the expression of cytokines, such as CCL3, CCL4, CCL20, IL-1α, IL-1β, IL-6, IL-8, and IL-10, among others, is presumed to be associated with NPC occurrence and development." (PMID 39483474, 2024).
Nephropathy (2 papers, 2021 to 2023). A nonspecific term referring to disease or damage of the kidneys. "In humans, increased expression of the IL-8, CCL4, and CCL20 genes are involved in the pathogenesis of renal diseases." (PMID 37268977, 2023). "A study, comparing the inflammation status in DM with/without nephropathy, demonstrated that plasma levels of proinflammatory monocytes as well as circulatory inflammatory mediators, such as PAI-1, syndecan-1, VEGF, IL-1β, IL-1Ra, and CCL4, increased in nephropathy subjects." (PMID 34941711, 2021).
osteoarthritis (2 papers, 2020 to 2022). A noninflammatory degenerative joint disease occurring chiefly in older persons, characterized by degeneration of the articular cartilage, hypertrophy of bone at the margins and changes in the synovial membrane. "In osteoarthritis, up-regulated miR-495 can promote chondrocyte apoptosis through inhibition of the NF-kB signaling pathway by targeting CCL4." (PMID 32450789, 2020).
osteoporosis (2 papers, 2024 to 2025). A condition of reduced bone mass, with decreased cortical thickness and a decrease in the number and size of the trabeculae of cancellous bone (but normal chemical composition), resulting in increased fracture incidence. "In osteoporosis, chemokines that affect osteoblast and osteoclast activity include CCL5, CCL3, and CCL4." (PMID 41416066, 2025). "Elevated circulating levels of CCL2, CCL3, CCL4, and CCL5 have been reported in patients with osteoporosis, suggesting that excessive chemokine signaling may enhance osteoclast recruitment and inflammatory bone resorption." (PMID 41416066, 2025).
Pain (2 papers, 2018). An unpleasant sensory and emotional experience associated with actual or potential tissue damage, or described in terms of such damage. "CCL4 has long been associated with neuropathic pain, while muscle pain in fibromyalgia is associated with high levels of the related chemokine CCL2." (PMID 29927949, 2018).
prostate (2 papers, 2015 to 2019).
psychosis (2 papers, 2019 to 2025). "CCL4 plasma levels were consistently elevated in all cases, and CCL4 elevation has also been described in first episode psychosis, and in young adults with high levels of depressive symptoms." (PMID 39304742, 2025).
pulmonary TB (2 papers, 2016 to 2022). "Humoral immunity is also stimulated at the site of disease: pulmonary TB is associated with an increase in the Th2 cytokines IL-4, CCL-4 and SOCS3 in bronchoalveolar lavage (BAL) fluid taken from patients with active pulmonary TB." (PMID 27865379, 2016).
retinal degeneration (2 papers, 2016 to 2023). Degeneration of the retina. "Several lines of evidence suggest that Ccl3, Ccl4, and Il6 are important mediators of pathogenic activity by macrophages in retinal degeneration, which may account for the neuroprotective action of NR58-3.14.3." (PMID 26911327, 2016). "Novel peaks were also seen at the Ccl3 and Ccl4 chemokine genes, as well as the interferon activated gene Ifi204 and the Cd68 surface marker —both of which were shown to become acutely accessible in a light damage model of retinal degeneration." (PMID 37880237, 2023).
Salmonella Infections (2 papers, 2017 to 2018). Infections with bacteria of the genus SALMONELLA. "On the other hand, FOXO signaling (TNFSF10, PRKAB1, GADD45B, STK4, STAT3), Salmonella infection (ARPC2, ARPC5L, CCL3L3, CCL4) and lysosome (LAPTM4B, HGSNAT, CD164, ATP6V0A2) pathways were up-regulated, albeit weakly, in the HLA-DR- Teff subset." (PMID 30231065, 2018). "CCL4, IL8L1 and CDC42 were contained in the Salmonella infection pathway and were all targeted by miR-34a." (PMID 28086873, 2017).
schistosomiasis (2 papers, 2011 to 2012). An infectious disease caused by parasitic trematodes of the genus Schistosoma that colonize human blood vessels and release eggs that can cause granulomatous reactions leading to acute (swimmer's itch or acute schistosomiasis syndrome) or chronic disease. "CCL4 and CCL21 were reported in the liver of mice with schistosomiasis." (PMID 22905138, 2012).
septic shock (2 papers, 2023 to 2024). Shock caused by infection; frequently caused by gram negative bacteria, although some cases have been caused by other bacteria, viruses, fungi, and protozoa; characterized by fever, chills, tachycardia, tachypnea, and hypotension. "First, in septic shock, a secondary analysis of the Vasopressin and Septic Shock trial suggested that higher baseline levels of IL-3, IL-6, and CCL4 may identify patients as potential responders to glucocorticoids resulting in reduced mortality." (PMID 38441708, 2024).
systemic sclerosis (2 papers, 2018 to 2025). A chronic disorder, possibly autoimmune, marked by excessive production of collagen which results in hardening and thickening of body tissues. "In fact, there was a decrease in CCL4 expression (FC = 0.38) in systemic sclerosis–derived myeloid cells, the opposite pattern to that observed in NL." (PMID 39989459, 2025). "This analysis revealed that there was no significant and meaningful (fold change [FC] > 2) upregulation in the expression of SPP1, CCL4, CCL5, and CXCL9 in systemic sclerosis myeloid cells." (PMID 39989459, 2025). "Thus, to compare the expression of CCL4 and SPP1 in systemic sclerosis myeloid cells versus healthy skin myeloid cells, scRNA-seq data from all systemic sclerosis myeloid cells were binned together and compared to all healthy skin–derived myeloid cells." (PMID 39989459, 2025).
thrombosis (2 papers, 2021 to 2024). "Additionally, CCL4 could indicate the deterioration of BD, as extremely high expression of CCL4 mRNA was found in patients who suffer from thrombosis and CNS involvement in our validation cohort." (PMID 34975900, 2021).
abscess (1 paper, 2015). An inflammatory process characterized by the accumulation of pus within a newly formed tissue cavity which is the result of a bacterial, fungal, or parasitic infection or the presence of a foreign body. "Of the host genes tested, we found that transcripts encoding IL-8, IL1β, oncostatin M-like, CCR1, CXCR1 (IL8RA), CCL4 (MIP-1β) and CCL3 (MIP1α)-like proteins were among the most highly up-regulated transcripts during S. aureus abscess formation." (PMID 25719526, 2015).
acute GVHD (1 paper, 2026). "In contrast, elevated IL-6, IL-17A, PAI-1, IL-10, CX3CL1, CXCL1, and CCL4 levels were prognostic for quiescent cGVHD compared with patients with resolved acute GVHD only." (PMID 41798937, 2026).
acute monocytic leukemia (1 paper, 2015). Acute monoblastic leukemia (AML-M5), is one of the most common subtypes of acute myeloid leukemia (AML) that is either comprised of more than 80% of monoblasts (AML-M5a) or 30-80% monoblasts with (pro)monocytic differentiation (AML-M5b). "We thus investigated whether IDE could affect the chemotactic activity of CCL4 P8A in a human acute monocytic leukemia cell line, THP-1, using a modified Boyden chamber assay." (PMID 25636406, 2015).
acute myeloid leukemia (1 paper, 2025). Acute myeloid leukemia (AML) is a group of neoplasms arising from precursor cells committed to the myeloid cell-line differentiation. "A significant secretion of CCL3, CCL2, CCL4, CXCL1, and CXCL8 exists in acute myeloid leukemia (AML) cells." (PMID 40148973, 2025).
alopecia areata (1 paper, 2021). Loss of scalp and body hair involving microscopically inflammatory patchy areas. "For example, patients with alopecia areata were characterized by nominally higher concentrations of CCL4, compared to the controls, which might become significant in a larger cohort." (PMID 34830700, 2021).
Amoebiasis (1 paper, 2019). "In addition, the up-regulated DEGs were significantly enriched in 12 pathways such as NF-kappa B signaling pathway including LYN, LY96, CCL4, CD14; ECM-receptor interaction pathway including CD44, COL6A3, COL1A2, FN1 and Amoebiasis pathway including COL1A2, ITGB2, CD14, FN1." (PMID 31355054, 2019).
angioimmunoblastic T-cell lymphoma (1 paper, 2022). A mature T-cell non-Hodgkin lymphoma, characterized by systemic disease and a polymorphous infiltrate involving lymph nodes and extranodal sites. "In contrast, polyclonal T-cells had up-regulation of genes related to HTLV-1 infection (NFKBIA and EGR1), cytokine interaction (CCL4 and IL2RG), apoptosis, and inflammatory response, as well as genes down-regulated in angioimmunoblastic T-cell lymphoma (AILT)." (PMID 35464471, 2022).
aortic aneurysm (1 paper, 2009). A ruptured aneurysm located in the wall of the proximal portion of the descending aorta proceeding from the arch of the aorta. "Initially we confirmed the up-regulation of Il6, Ccl4, Ccl8 and MMP2 within aortic aneurysms using real time PCR." (PMID 19580648, 2009).
Arterial stenosis (1 paper, 2022). Narrowing or constriction of the inner surface (lumen) of an artery. "Furthermore, the higher grades of arterial stenosis in the CAD group were associated with higher levels of CCL3 and CCL4 gene expression." (PMID 36381642, 2022).
astrocytoma (1 paper, 2022). "Genes that show higher expression in astrocytoma compared to glioblastoma were CX3CL1, CSF1 (MCSF), CCL3 (MIP1α), CCL4 (MIP1β), TGFα, FLT3LG, CXCL5, CCL19 while KITLG (SCF) and NGF were equally expressed in the two tumor types." (PMID 35301393, 2022).
atopic asthma (1 paper, 2021). An asthma that is characterized by symptoms that are triggered by an allergic reaction caused by inhaled allergens such as dust mite allergen, pet dander, pollen and mold. "We speculate that IL2RG and CCL4 might be important genes related to childhood atopic asthma, and together with CCL2 participate in the cytokine receptor interaction signaling pathway that plays a role in childhood atopic asthma." (PMID 34525985, 2021).
atrophic gastritis (1 paper, 2020). "In an atrophic gastritis environment, the expression of CXCL14, CCL4, CCL26, CCL21, CCL2, CCL19, and CCL13 was correlated with the infiltration of central memory CD4 T cell." (PMID 33426088, 2020).
bacterial meningitis (1 paper, 2019). Inflammation of the membranes surrounding the brain and spinal cord due to a bacterial infection. "In bacterial meningitis, multiple cytokines including CXCL10 (IP10), CCL2, CCL7 (MCP-3), CCL4 (MIP-1β), CCL5, CXCL12, IL6, IL8, and IL17 have been shown to be increased in the acute phase of the disease (; Pinto)." (PMID 31727097, 2019).
bacterial pneumonia (1 paper, 2021). Acute infection of the lung parenchyma caused by bacteria (e.g., Streptococcus pneumoniae, Haemophilus influenzae, Chlamydia pneumoniae, Mycoplasma pneumoniae, and Legionella pneumophila). "Notably, recombinant CCL4 protein could enhance the protective effect on S. aureus-induced secondary pulmonary infection of septic mice, which indicated that BPS-induced CCL4 partially mediated resistance to secondary bacterial pneumonia." (PMID 34054345, 2021).
bacterial vaginosis (1 paper, 2011). Infection caused by bacterial overgrowth in the vagina. "Indeed, bacterial vaginosis has been associated with increased levels of IL-1 beta, IL-6, IL-8, IL-10 and TNF-alpha, RANTES (CCL5), macrophage inflammatory protein (MIP-1 alpha/CCL3) and MIP-1 beta (CCL4) in genital samples." (PMID 21966450, 2011).
bone resorption (1 paper, 2024). The process in which specialized cells known as osteoclasts degrade the organic and inorganic portions of bone, and endocytose and transport the degradation products. "Studies have concluded that CCL4 can promote OC invasion and induce bone resorption disease through OC differentiation gene expression profiling." (PMID 38757000, 2024).
brain glioma (1 paper, 2024). A malignant glioma that involves the brain. "This study offers important insights into the potential of serum CCL4 levels as a biomarker for differentiating between brain gliomas and central nervous system inflammatory diseases, but it also has several limitations." (PMID 39364412, 2024). "CCL4 may serve as a potential biomarker to distinguish between brain gliomas and brain inflammation in serum." (PMID 39364412, 2024).
bronchiolitis (1 paper, 2019). Inflammation of the bronchioles characterized by swelling of the bronchioles and mucus accumulation. "Indeed, elevated levels of IL-6, IL-8 (CXCL8), CCL2, and CCL4 have been reported in cerebrospinal fluid from patients with severe bronchiolitis and hRSV-associated encephalopathy." (PMID 30936869, 2019).
brucellosis (1 paper, 2024). Brucellosis is a bacterial infection that spreads from animals to people via unpasteurized dairy products or by exposure to contaminated animal products or infected animals. "We found that NK cells, especially for NK_Naive, NK_Memory and NK_CD56(dim), in brucellosis patients potentially underwent migration, with several migration‐related genes highly expressed like CCL4, CXCR5, CCL18, CXCL2, and so forth." (PMID 39135683, 2024). "As the major contributor of potential inflammatory storm, many inflammatory response genes (e.g., ITGB2, OSM, FPR1, CEBPB, NINJ1) and canonical pro‐inflammatory cytokines (e.g., CXCL8, CCL3, CCL4, TNF, IL1B, S100A12) were expressed at higher levels in brucellosis patients than in healthy donors." (PMID 39135683, 2024). "Procarta cytokine analysis from the plasma of these individuals, supported the finding that brucellosis patients, especially for acute patients, had a higher level of multiple pro‐inflammatory cytokines, such as CXCL8/IL8, CCL3/MIP‐α, CCL4/MIP‐β, TNF/TNF‐α, IL1B/IL1‐β." (PMID 39135683, 2024).
cholangiocarcinoma (1 paper, 2020). A carcinoma that arises from the intrahepatic biliary tree (intrahepatic cholangiocarcinoma) or from the junction, or adjacent to the junction, of the right and left hepatic ducts (hilar cholangiocarcinoma). "In contrast, mononuclear phagocytes exhibited up‐regulation of chemokines such as CCL4, CCL4L2, and CCL3L3 in the cholangiocarcinoma samples and extracellular remodeling genes such as MMP19, MMP12, and HS3ST2 in the metastatic patients." (PMID 33332768, 2020).